CLDN5 (claudin 5)
Diseases named in the same sentence as CLDN5 in open-access papers (continued):
Sharing a sentence is not in itself a finding about the gene and the disease.
Stroke (continued). "The increased CLDN5/ZO1 ratio was evaluated in the patients hospitalized, less than 6 h after the onset of a stroke, discriminated between the groups of ischemic stroke patients with and without a hemorrhagic transformation." (PMID 36293204, 2022). "We further studied such complexes using markers for tight-junction proteins (occludin and claudin-5) and proteases (MMP2 and MMP9) that increase the permeability of the BBB during stroke." (PMID 32221863, 2021). "As such, this present study was designed to assess the effects of STVNA in our in vitro stroke model of the BBB.The integrity and permeability of the BBB are governed and maintained by tight junction proteins (TJPs) such as claudin-5 and occludin." (PMID 33192319, 2020). "During a stroke, the BBB gets damaged, which is accompanied by changes in the concentrations and distributions of claudin-5, occludin, ZO-1, and other building blocks of the BBB." (PMID 33182224, 2020). "Rodent models have revealed that stroke and traumatic brain injury (TBI) are characterised by a biphasic opening of the BBB with downregulation of tight junction proteins including claudin-5, occludin and ZO-1 and subsequent extravasation of serum proteins." (PMID 30691500, 2019). "In stroke, vascular endothelial cell (EC) dysfunction at the compromised BBB involves paracellular leakage, as evidenced by the degradation of tight junction (TJ) proteins including claudin-5 (CLDN5), occludin (OCLN), and zonula occludens-1 (ZO-1/TJP1)." (PMID 40866935, 2025). "In addition, salidroside reversed the decrease in tight junction proteins (such as claudin-5 and occludin) by inhibiting the activation of MMP-9 (a member of MMPs), which proved the improvement of BBB damage in experimental stroke rat models." (PMID 35462916, 2022). "For example, in the early (acute) phase of stroke, NVU dysfunction is characterized by disruption of BBB integrity/BBB breakdown (disassembly of TJ complex, decreases in the TJ proteins claudin-5, occludin, and ZO-1) that leads to vasogenic brain edema, a life-threatening acute stroke complication." (PMID 31543756, 2019). "Using eGFP:claudin-5 transgenic mice to selectively visualise endothelial tight junctions, ultrastructural changes including gaps between adjacent endothelial cells and absence of tight junctions was apparent 48–58 h after stroke but not before." (PMID 30691500, 2019). "ELISA results showed that blood claudin-5 levels did not change significantly during the first 4.5 hours of cerebral ischemia, which might be due to the fact that claudin-5 protein is resistant to proteolytic degradation under stroke conditions." (PMID 28079139, 2017). "In comparison to the Veh stroke brains, ZT-1a-treated stroke brains, but not the BMT-treated, exhibited statistically significant preservation of Claudin-5 protein expression in the ChP (p < 0.05)." (PMID 35413993, 2022). "Furthermore, no assessable difference was observed in claudin-5 coverage in VEGF-GOF and VEGF-LOF 14- and 28-day post-stroke." (PMID 35175562, 2022). "In other studies of stroke, JAM-A, ZO-1, and claudin-5 were found not to correlate with blood-brain barrier breakdown in the acute phase; however, a decrease in claudin-5 levels may indicate improved barrier function by 10 days." (PMID 30259344, 2018).
ischemic stroke (48 papers, 2011 to 2025). A stroke disorder caused by obstruction of blood flow to the brain, due to thrombotic (local blood clot formation) or embolic (due to a blood clot or other material traveling from another site) event. "Our results showed that QKL protected the TJs including ZO-1, claudin-5, VE-Cadherin, and occludin from damage caused by ischemic stroke." (PMID 32908557, 2020). "Fasudil, a Rho kinase inhibitor, is studied to prevent stress fiber formation and preserve the distribution of TJ proteins such as claudin-5 and occludin following ischemic stroke." (PMID 41361096, 2025). "Our in vivo data suggest that endothelial Rab7 elimination is more effective in reducing abnormal ZO-1 localization at BBB cell junctions after ischemic stroke compared to eGFP::Claudin-5 and VE-Cadherin proteins and preserving their total protein levels." (PMID 41024170, 2025). "Overall, these data show that Rab7a elimination in BECs predominantly reduces ZO-1 degradation and localization to cell junctions compared to Claudin-5 or VE-Cadherin during the acute BBB damage after ischemic stroke." (PMID 41024170, 2025). "Our analysis demonstrated that claudin 5 expression was preserved in the microvasculature at the lesion site 1 week after ischemic stroke upon increasing PDGF-D subacute bioavailability." (PMID 38769116, 2024). "The second most cited article titled “Matrix metalloproteinase-2-mediated occludin degradation and caveolin-1-mediated claudin-5 redistribution contribute to BBB damage in the early stage of ischemic stroke” was published in The Journal of Neuroscience." (PMID 39119484, 2024). "As is similar to our findings for patients with MCI or AD, circulating CLDN-5 levels are elevated in other CNS diseases, including ischemic stroke, bipolar disorder, and obsessive–compulsive disorder." (PMID 38338697, 2024). "Claudin-5, as the most prominently expressed tight junction protein in the BBB, exhibits a close association with ischemic stroke pathology." (PMID 38193092, 2023). "In experimental models of pathological conditions, such as ischemic stroke, claudin-1 is lost in the cerebral vasculature, claudin-5 expression is reduced, and the interaction between claudin-5 and occludins is disrupted." (PMID 37840921, 2023). "Elected levels of MMP12 after ischemic stroke was reported to degrade several tight junction proteins including claudin-5, occludin and ZO-1." (PMID 35382832, 2022). "Genetic deletion of miR-34a effectively reduced the BBB leakage, alleviated the disruption of tight junction proteins ZO-1, claudin-5, and occludin, and improved neurological recovery following ischemic stroke." (PMID 35346266, 2022). "The NF-κB/MMP-9 signaling pathways contribute to the degradation of claudin-5, prompting hemorrhagic transformation in ischemic stroke." (PMID 35456999, 2022). "The expression of tight junction proteins zo-1, occludin-1 and claudin-5 decreased after ischemic stroke." (PMID 36467061, 2022). "As a predictor of a hemorrhagic transformation in ischemic stroke patients, the CLDN5/ZO1 ratio had the highest sensitivity and an even higher specificity than S100B." (PMID 36293204, 2022). "The results showed that compared with the Sham group, the expression levels of claudin-5,cocludin-1 and zo-1 proteins in the Model group rats decreased, indicating that the intestinal barrier of ischemic stroke rats was damaged." (PMID 36467061, 2022). "As MMP-9 was the primary proteolytic enzyme, which was reported to degrade claudin-5 and ZO-1 after ischemic stroke, Con-exo significantly inhibited the level of MMP-9 compared with the MCAO group (P < 0.01)." (PMID 35308117, 2022). "Perampanel, an AED similar to RUF, acts as a non-competitive AMPA receptor antagonist and provides a protective effect against ischemic stroke through claudin 5-mediated permeability regulation of BBB." (PMID 34514163, 2021).
ischemic stroke (continued). "The clinicopathological characteristics of the BBB after ischemic stroke are evacuation of the TJ structure between ECs, a decrease in Claudin-5 protein expression, and an increase in permeability." (PMID 34531766, 2021). "ZO-1, VE-cadherin and Claudin-5 are important mediators of endothelial adherence junction and angiogenesis, and are vital in maintaining the blood-brain barrier balance in ischemic stroke." (PMID 34612779, 2021). "OPCs transplantation reduced IgG leakage, rescued claudin-5 disruption in ischemic stroke, which suggested that OPCs transplantation protected BBB integrity through reducing tight junction protein degradation." (PMID 31907363, 2020). "New born Cldn5-deficient mice showed increased passage of such tracers across the blood brain barrier, whereas the ultrastructure of tight junctions were unaffected and in a model of ischemic stroke, Cldn5 was targeted by matrix metalloproteinases." (PMID 32670077, 2020). "To further confirm the impairment of BBB after ischemic stroke, we evaluated the levels of tight junction protein complexes namely, claudin-5 and ZO-1." (PMID 30705764, 2019). "The largest study identified included 458 patients and found that the serum levels of claudin-5, occludin, and the claudin-5-to-ZO-1 ratio were significantly increased in patients with hemorrhagic conversion of ischemic stroke." (PMID 30259344, 2018). "The prognostic value of serum claudin-5 in hemorrhage conversion of ischemic stroke highlights its utility as a marker of endothelial barrier breakdown following mechanical and ischemic damage." (PMID 30259344, 2018). "Consistent with the data acquired in 2 dimensions, our 3-dimensional quantitative data also indicated decreased claudin-5 positive signals in the penumbra 24 hours after ischemic stroke." (PMID 29896415, 2018). "Reports have found that degradation of claudin-5 and occludin can increase the permeability and contribute to brain oedema in ischaemic stroke." (PMID 30170602, 2018). "When an ischemic stroke results in the functional impairment of cellular components, the disruption of tight junction proteins, such as Claudin-5 and GLUT-1, could lead to an increase in the permeability of the BBB." (PMID 40530334, 2025). "And in BBB damage after ischemic stroke, ZO-1 and Claudin-5 were both documented to be degraded via autophagy-lysosome 21, 22, which were in accord with our finding to find ZO-1 and Occludin were damaged via autophagy-lysosome pathway after ischemic stroke." (PMID 39781452, 2025). "To understand how Rab7a affects the disassembly of BBB tight and adherens junctions during the acute phase of ischemic stroke, we analyzed the morphology of eGFP::Claudin-5+, ZO-1+ TJs and CDH5+ AJs at 48 hours after t-MCAO by immunofluorescence and electron microscopy." (PMID 41024170, 2025). "10-O-(N, N-dimethylaminoethyl) ginkgolide B methanesulfonate (XQ-1H) has been shown to normalize the expression of claudin-5, occludin, ZO-1, and β-catenin in ischemic stroke model mice, leading to reduced BBB permeability and protection against oxygen–glucose deprivation/reoxygenation injuries." (PMID 39030617, 2024). "Notably, claudin-5, the most prominently expressed tight junction protein at the BBB, is closely associated with the pathology of ischemic stroke." (PMID 38193092, 2023). "Recent evidence indicates that autophagy is involved in claudin-5, occludin, and ZO-1 degradation after ischemic stroke and we further examined whether serum exosomes preserved tight junction proteins through autophagy." (PMID 35308117, 2022). "It has been documented that claudin-5 is targeted for degradation by matrix metalloproteinase after an ischemic insult, and the loss of claudin-5 is responsible for the disruption of the BBB in ischemic stroke." (PMID 35456953, 2022).
ischemic stroke (continued). "By contributing to tight junctions, the transmembrane proteins Occludin and Claudin-5 as well as the membrane-associated protein ZO-1 in vascular endothelial cells can help maintain or restore BBB integrity, yet they are down-regulated after ischemic stroke." (PMID 32184732, 2020). "Moreover, the vitamin D receptor was demonstrated to mediate the protective effect of vitamin D-induced expression of occludin, claudin-5 and zonula occludens in ischemic stroke." (PMID 31930458, 2020). "Further verifying our findings about the pivotal role of both SDF-1 receptors on stabilizing cellular integrity, inhibition of CXCR4 increased TJP-1, occludin, and claudin 5 in the blood/brain barrier in terms of an ischemic stroke and brain-specific metastasis in lung cancer." (PMID 32210974, 2020). "Based on our results, GSH may prevent the degradation of the tight junction protein claudin-5 following ischemic stroke, which may involve the reduced translocation of FOXO3 into the nucleus." (PMID 25722793, 2015). "To verify whether FtMt overexpression increases the BBB integrity by attenuating the degradation of junction-related proteins that occurs after ischemic stroke, we immunofluorescence-stained the tight junctional molecules claudin-5, occludin and ZO-1, along with the endothelial marker CD31." (PMID 35883748, 2022). "The decrease in TJ proteins, CLDN-5, OCLN, and ZO-1, was observed in ischemic stroke and traumatic brain injury animal models and in TJ-related proteins in animal models of CNS inflammation such as multiple sclerosis." (PMID 35935952, 2022). "miR-150 expression was significantly suppressed under hypoxia or ischemic stroke, upregulation of miR-150 exhibited worse BBB permeability and decreased claudin-5 expression in both in vitro and in vivo ischemic stroke models." (PMID 35346266, 2022). "TJPs including ZO-1, Claudin-5, and Occludin are important in regulating the integrity and permeability of BBB and are disrupted and redistributed after ischemic stroke." (PMID 36186136, 2022). "MMP inhibitors can also significantly block the degradation of claudin-5 and angiotensin after focal cerebral infarction, thus alleviating BBB damage in the early periods of ischemic stroke." (PMID 33584203, 2020). "Progesterone and allopregnanolone reduce neuroinflammation and improve barrier function in a mouse model of ischemic stroke by downregulating MMP expression and preventing degradation of claudin-5 and occludin." (PMID 30691500, 2019). "Ischemic stroke compromises BBB integrity, which is mediated by cytoskeleton rearrangement, and redistribution and disappearance of tight junction proteins such as claudin 5 and occludin in brain endothelial cells, resulting in increased BBB permeability." (PMID 24991401, 2014). "Increased expression and activity of several matrix metalloproteases (MMPs; e.g., MMP2 and MMP9) after ischemic stroke contributes to acute BBB damage by cleaving the extracellular domains of several adherens (VE-Cadherin) and tight (Claudin-5, Occludin) junction proteins in BECs." (PMID 41024170, 2025). "In summary, the findings of the present study indicated that miR-199a-5p inhibited inflammation following ischemic stroke by activating the PI3K/Akt signaling pathway, reduced neuronal apoptosis in the ischemic penumbra, and upregulated Claudin-5 and VEGF to preserve the integrity of the BBB." (PMID 39302945, 2024). "Moreover, several studies in ischaemic stroke, a neurological disease characterized by BBB impairment, suggest that the breakdown of claudin-5 can be attributed to VEGF-mediated matrix metalloproteinase (MMP) expression." (PMID 35836182, 2022). "Claudin 5 has been suggested to be a prominent candidate in BBB maintenance and regulation to treat ischemic stroke and may be a viable target for preventative treatment in people who experience spreading depression." (PMID 36015292, 2022).
ischemic stroke (continued). "In the setting of experimental ischemic stroke, activation of G protein-coupled estrogen receptor 1 ameliorated BBB permeability following four vessel occlusion in ovariectomised rats and restored expression levels of claudin-5." (PMID 30691500, 2019). "Consistent with our results obtained from ischemic stroke rats, ischemia and reperfusion induced a reduction in occludin protein, but not claudin-5, in wild-type mice, and NBO treatment significantly reversed this reduction." (PMID 22146586, 2011). "Similarly, BBB damage in the early phase of ischemic stroke leads to a claudin-5 re-localization, but no change in overall protein levels is observed." (PMID 33924251, 2021).
depression (40 papers, 2018 to 2026). "We report that environmental enrichment dampens stress-induced loss of endothelial tight junction Claudin-5 (Cldn5) along with anxiety- and depression-like behaviors in male mice via an increase in fibroblast growth factor 2 (Fgf2)." (PMID 41545369, 2026). "Given evidence for a role for CLDN5 in susceptibility to depression following stress, and phenotypic and genetic similarities between PTSD and depression, our aim was to examine, for the first time, the association between PTSD and CLDN5 epigenetics." (PMID 41358302, 2025). "A UK Biobank candidate SNP study with over 275k individuals found that CLDN5 variant rs885985 interacted with an IL-6 variant and self-reported life stress to predict depression (i.e., a 3-way interaction effect), and this was replicated in a second cohort." (PMID 41358302, 2025). "Two of these trauma and PTSD-associated probes (the peak probe, cg21872764 and cg17411190) also showed associations with PTSD when methylation was measured in vmPFC, a region previously implicated in postmortem CLDN5 expression studies of depression." (PMID 41358302, 2025). "Fourth, multiple sclerosis (MS) is a neurodegenerative disease showing increased CLDN-5 levels, whereas major depressive disorder and schizophrenia are psychiatric disorders associated with increased and decreased plasma and serum CLDN-5 levels, respectively." (PMID 38338697, 2024). "Studies of these “rodent models” of depression have implicated claudin-5 in the relationship between stress, NVU dysfunction, and depressive-like behaviors." (PMID 39157756, 2024). "Brain region-specific knockdown of CLDN-5 using adeno-associated virus (AAV) in mice has also clearly shown that increased BBB permeability in the prefrontal cortex sufficed to induce depression-like behaviors with impaired memory." (PMID 38898501, 2024). "Down-regulation of the Claudin-5 has been confirmed to cause both anxiety- and depression-like behaviors during subthreshold stress." (PMID 36051441, 2022). "Transient knockdown of claudin-5 in the nucleus accumbens is associated with exacerbated depression-like behaviours in the chronic social defeat model of depression." (PMID 30691500, 2019). "Following just 10 days of repeated social defeat, claudin 5 (Cldn5) mRNA and protein expression were reduced in the NAc of stress-susceptible mice that exhibited depression-related behavioral phenotypes when compared to resilient mice and unstressed controls." (PMID 30102966, 2018). "In our previous study, we found a significant association between the functional polymorphism of CLDN5 and stress-associated depression only when taking into account the influencing properties of the widely studied polymorphism (rs1800795) of the interleukin-6 proinflammatory cytokine." (PMID 39457114, 2024). "Claudin-5 is the most enriched tight junction protein at the blood–brain barrier, and its dysfunction has been implicated in Alzheimer’s disease, multiple sclerosis and psychiatric disorders, including depression and schizophrenia." (PMID 38338705, 2024). "Importantly, loss of tight junction CLDN5 expression was confirmed in postmortem brains samples from women with major depressive disorder supporting relevance for human MDD." (PMID 35013188, 2022). "This loss of claudin-5 expression was also confirmed in postmortem brain samples from women with MDD, underscoring its relevance to human depression." (PMID 40725164, 2025). "At the BBB, S100B and claudin-5 are the most enriched proteins, and their dysfunction has been implicated in neuroinflammatory disorders such as MS, neurodegenerative diseases such as Alzheimer’s, and psychiatric disorders including depression and schizophrenia." (PMID 32085663, 2020).